TGFBR3L (transforming growth factor beta receptor 3 like)
Description:
Expressed in gonadotrope cells, acts as an inhibin B coreceptor and regulates follicle-stimulating hormone (FSH) levels and female fertility.
Synonyms: TGFR-3L; GEMP
Tractability: Antibody: UniProt places it where antibodies can reach, with high confidence; UniProt predicts a signal peptide or a membrane-spanning region; its Gene Ontology location is reachable by antibodies, with medium confidence.
Gene: Protein-coding gene on chromosome 19 (7,914,803 to 7,919,097, forward strand). Ensembl gene ENSG00000260001.
Subcellular location: Cell membrane
Subcellular location (Human Protein Atlas): Vesicles
Gene Ontology:
Molecular function: glycosaminoglycan binding; transforming growth factor beta binding; transforming growth factor beta receptor activity; type II transforming growth factor beta receptor binding
Biological process: cell migration; epithelial to mesenchymal transition; regulation of transforming growth factor beta receptor signaling pathway; transforming growth factor beta receptor signaling pathway
Cellular component: plasma membrane
Genetic constraint (gnomAD): Loss-of-function variants: 21 observed, 15.29 expected, observed/expected ratio (o/e) 1.37, 90% interval 0.97 to 1.86. The synonymous counts are far from expectation, so gnomAD's model fits this gene poorly and the ratio says little. Missense variants: 479 observed, 386.36 expected, observed/expected ratio (o/e) 1.24, 90% interval 1.15 to 1.34. Synonymous variants: 245 observed, 185.57 expected, observed/expected ratio (o/e) 1.32, 90% interval 1.19 to 1.47.
Homologues: Orthologues: chimpanzee TGFBR3L (94% identical), macaque TGFBR3L (93% identical), rabbit TGFBR3L (84% identical), pig TGFBR3L (83% identical), mouse Tgfbr3l (76% identical), rat Tgfbr3l (75% identical), guinea pig TGFBR3L (73% identical). Paralogues in human: TGFBR3 (25% identical), ENG (13% identical).
Diseases named in the same sentence as TGFBR3L in open-access papers:
TGFBR3L is named in the same sentence as 7 diseases in open-access papers, as found by Europe PMC text mining. Sharing a sentence is not in itself a finding about the gene and the disease. The quoted sentences say what the papers report.
neuroblastoma (2 papers, 2020 to 2023). Neuroblastoma (NB) is the most common solid, extracranial childhood tumor. "Increased expression of TGFBR3L has also been associated with development of neuroblastomas, and a more aggressive phenotype." (PMID 36952069, 2023). "Single nucleotide polymorphism (SNP) in TGFBR3L has been associated with the risk of neuroblastoma, especially primary neuroblastoma in the adrenal gland." (PMID 33396509, 2020).
female infertility (1 paper, 2022). Diminished or absent ability of a female to achieve conception. "Recently generated Tgfbr3l gene-disrupted female mice showed increased FSH production and follicle development relative to controls, and double knockout of Tgfbr3l and betaglycan resulted in female infertility, indicating an important role of this factor in female reproductive function." (PMID 36613635, 2022).
pituitary tumours (1 paper, 2020). "In conclusion, TGFBR3L is a novel pituitary gland specific protein, located in the membrane of gonadotroph cells in non-neoplastic anterior pituitary gland and in a subset of gonadotroph pituitary tumours." (PMID 33396509, 2020). "Whether TGFBR3L is useful, as an additional marker for characterisation of “null-cell” tumours needs to be clarified in larger cohort of pituitary tumours that fulfils criteria for “null cell adenoma”." (PMID 33396509, 2020). "Further, we characterised and correlated the distribution of TGFBR3L to previously known markers of pituitary cell differentiation and EMT in the pituitary tumours." (PMID 33396509, 2020). "In a search for additional specific biomarkers for pituitary tumours, we describe here the distribution of TGFBR3L in non-neoplastic anterior pituitary tissue and in a well-characterised cohort of patients with PitNETs." (PMID 33396509, 2020).
Tumours (4 papers, 2020 to 2024). "We have recently demonstrated that FSH staining in gonadotroph tumours, similar to TGFBR3L, is associated with lower membranous E-cadherin, increased nuclear E-cadherin and increased ERα staining." (PMID 33396509, 2020). "The weakly positive nature of the TGFBR3L staining may also affect the association with tumour volume." (PMID 36952069, 2023). "We found a weak association between TGFBR3L and preoperative tumour volume." (PMID 36952069, 2023). "TGFBR3L staining was present in 52% (n = 60) of the gonadotroph tumours, and in one double-PitNET (positive for FSHβ and SF-1 in some cells, and for ACTH and T-Pit in others), while all other tumours were negative." (PMID 36952069, 2023). "The expression profile of TGFBR3L was heterogeneous within the tumour cell population, and positive cells often displayed a perivascular location." (PMID 33396509, 2020). "The potential role of TGFBR3L in tumorigenesis related to SF-1 needs to be explored in other neoplasms." (PMID 33396509, 2020). "In total, 230 different tumours were stained, and TGFBR3L staining was exclusively seen in the gonadotroph tumours." (PMID 33396509, 2020). "TGFBR3L immunoreactivity was observed in gonadotroph tumours only and demonstrated intra-tumour heterogeneity with a perivascular location." (PMID 33396509, 2020). "We verified the location of TGFBR3L protein in gonadotroph cells as well as in gonadotroph tumours only." (PMID 33396509, 2020). "In our cohort of PitNETs, TGFBR3L was positive in slightly more than one-third of the gonadotroph tumours." (PMID 33396509, 2020). "TGFBR3L staining was selectively present in 52% of gonadotroph tumours." (PMID 36952069, 2023). "However, 46.4% of the LHβ positive tumours and 66.7% of both FSHβ and LHβ positive tumours presented positive TGFBR3L staining (p < 0.001)." (PMID 36952069, 2023). "Another explanation could be that the two cohorts of gonadotroph tumours may differ by other means due to inclusion bias, leading to a real difference in the TGFBR3L expression." (PMID 36952069, 2023). "Furthermore, tumours positive for TGFBR3L also had a nuclear accumulation of E-cadherin suggesting a possible role of TGFBR3L in tumour aggressiveness." (PMID 36952069, 2023). "Postoperative MRI follow-up studies could more precisely unveil differences in tumour aggressiveness based on the presence of TGFBR3L." (PMID 36952069, 2023). "As compared to our previous study performed in a retrospective cohort of PitNETs tissue microarrays, where we found that one third of the gonadotroph PitNETs were TGFBR3L positive, the percentage of positive tumours in this study was slightly higher (i.e. one half)." (PMID 36952069, 2023). "This might be due to the difference in assessing tissue microarray vs. whole tumour slides where larger areas of tumour tissue are examined, as a degree of intra-tumour heterogeneity in the TGFBR3L staining." (PMID 36952069, 2023). "Furthermore, we found that TGFBR3L correlated with tumour FSH and LH staining, and 3-plex staining revealed an overlap of TGFBR3L positive cells, SF1, as well as FSH and LH positivity." (PMID 33396509, 2020). "Of the 110 gonadotroph tumours, 37 (34%) showed positive immunolabelling for TGFBR3L." (PMID 33396509, 2020). "As our study was based on TMAs, and TGFBR3L positivity shows intra-tumour heterogeneity, we cannot exclude that even a higher proportion of gonadotroph tumours may be TGFBR3L positive." (PMID 33396509, 2020). "Tumours positive for TGFBR3L also had a nuclear accumulation of E-cadherin more frequently." (PMID 33396509, 2020). "Further studies are needed to better characterise the heterogeneity, which could also be due to environmental factors in the tumours, especially since we observed a perivascular location of TGFBR3L positive tumour cells." (PMID 33396509, 2020). "TGFBR3L staining correlated with tumour FSH-β and LH-β staining." (PMID 33396509, 2020).
Tumours (continued). "In addition, there was a negative association between TGFBR3L tumour staining and circulating gonadotropins in males, also when excluding patients receiving sexual hormone substitution." (PMID 36952069, 2023). "The UMAP plots showed that the LHB, GNRHR, TGFBR3L, FOSB and SCGN genes were highly expressed mainly in the epithelial cells of the normal group, while their expression was low in the epithelial cells of the tumour group." (PMID 39548559, 2024). "The gonadotroph tumours staining for both TGFBR3L and TGFBR3 (n = 10) did not deviate from the rest of the gonadotroph cohort in regards to age, gender, staining for FSH and LH, tumour volume or cavernous sinus invasion (data not shown)." (PMID 36952069, 2023). "Fifteen (27%) of the TGFBR3L negative tumours and 17 (28%) TGFBR3L positive tumours were considered invasive, p = 0.89)." (PMID 36952069, 2023). "TGFBR3L was associated to IRS of LHβ (median 2 [IQR 0–3] in TGFBR3L negative and median 6 [IQR 3–9] in TGFBR3L positive tumours, p < 0.001), but not to the IRS of FSHβ (p = 0.32)." (PMID 36952069, 2023). "Fifteen (28%) of the TGFBR3L negative gonadotroph tumours and 10 (17%) of the TGFBR3L positive tumours also stained positive for TGFBR3 (p = 0.18)." (PMID 36952069, 2023). "We found that the groups staining for either FSHβ, LHβ or both more often presented staining for TGFBR3L than tumours not staining for the gonadotropins." (PMID 36952069, 2023). "The hormone negative but SF1 positive gonadotroph tumours were more often TGFBR3L negative than tumours staining for LHβ alone or both FSHβ and LHβ." (PMID 36952069, 2023). "Only four tumour samples presented between 10 and 30% (n = 3) or ≥ 30% cells (n = 1) positive for TGFBR3L, and for the purpose of further statistical analyses, we decided to dichotomize into negative and positive tumours." (PMID 36952069, 2023). "The difference in LHβ IRS between TGFBR3L negative and positive gonadotroph tumours remained significant when investigating postmenopausal women alone and in males without testosterone substitution (data not shown)." (PMID 36952069, 2023). "When investigating the different subgroups of gonadotroph tumours we found that none of the tumours staining for FSHβ alone (n = 6) and only one of the tumours not staining for neither FSHβ nor LHβ (n = 12) presented positive for TGFBR3L." (PMID 36952069, 2023). "The function of TGFBR3L is currently unknown, but the results suggest a role in gonadotroph cell development and function based on the correlation with FSH/LH and possibly tumour progression related to the epithelial-to-mesenchymal transition process." (PMID 33396509, 2020). "The gonadotroph-specific nature of TGFBR3L, a correlation to both FSH and LH as well as an inverse correlation to membranous E-cadherin and oestrogen receptor β suggests a role in gonadotroph cell development and function and, possibly, tumour progression." (PMID 33396509, 2020). "We also explored how TGFBR3L correlated with oestrogen receptor (ER) and somatostatin receptors (SSTR), which are additional markers that we have explored previously in gonadotroph tumours." (PMID 33396509, 2020). "We could not prove a relation between the staining for TGFBR3L and preoperative cavernous sinus invasion, and the relation to tumour volume should be interpreted cautiously." (PMID 36952069, 2023). "Presence of TGFBR3L was associated with a higher IRS of LHβ in gonadotroph NF-PitNETs (median 2 [IQR 0–3]) in TGFBR3L negative and median 6 [IQR 3–9]) in TGFBR3L positive tumours, p < 0.001)." (PMID 36952069, 2023). "This was also the case when considering males (LHβ IRS median 2 [IQR 1–3] in the negative and median 6 [IQR3-9] in TGFBR3L positive tumours, p < 0.001) and females (LHβ IRS median 2 [IQR 0–3] in negative and median 6 [IQR3-9] in positive TGFBR3L tumours, p < 0.001)." (PMID 36952069, 2023).
Tumours (continued). "The over representation of TGFBR3L negative tumours among the hormone negative gonadotroph NF-PitNETs might point to these tumours being less differentiated than the hormone positive tumours." (PMID 36952069, 2023). "Furthermore, TGFBR3L staining was not related to invasive tumour growth into the cavernous sinus, age or gender." (PMID 36952069, 2023). "Interestingly, when examining the intra-tumour heterogeneity for FSH/LH, an occasional perivascular location could also be observed, similar to the TGFBR3L location." (PMID 33396509, 2020). "None of the limited null-cell tumours in the present cohort stained positive for TGFBR3L." (PMID 33396509, 2020). "Of these, 30 gonadotroph tumours were TGFBR3L positive, while 65 were negative." (PMID 33396509, 2020). "Additionally, nuclear presence of E-cadherin was more frequently seen in tumours positive for TGFBR3L than in TGFBR3L negative tumours (90% vs. 71%, p = 0.039)." (PMID 33396509, 2020). "Also, no tumours exclusively staining for FSHβ, and not LHβ, presented TGFBR3L staining." (PMID 36952069, 2023). "The presence of TGFBR3L was associated with a higher preoperative tumour volume, median 4769 mm3 (IQR 3299–7896) in TGFBR3L negative tumours and median 7163 mm3 (IQR 4719–9511) in TGFBR3L positive tumours, p = 0.03." (PMID 36952069, 2023). "Finally, no relation between TGFBR3L and TGFBR3 staining was found, the latter being absent or expressed at a low level in the majority of gonadotroph tumours." (PMID 36952069, 2023). "TGFBR3L showed membranous immunolabeling and was found to be gonadotroph cell lineage-specific, verified by co-expression with SF1 and FSH/LH staining in both tumour and non-neoplastic anterior pituitary tissues." (PMID 33396509, 2020). "The function of TGFBR3L is thus far unknown, but the correlation to FSH-β and LH-β, as well as their co-localisation, suggest a gonadotroph–related function, both in the non-neoplastic anterior pituitary gland and in tumour cells." (PMID 33396509, 2020).
TGFBR3L also shares sentences with these, for which no sentence is quoted: adenoma (1 paper); neuroendocrine tumours (1); pituitary (1).